YEATS4 (YEATS domain containing 4)
Description:
Chromatin reader component of the NuA4 histone acetyltransferase (HAT) complex, a complex involved in transcriptional activation of select genes principally by acetylation of nucleosomal histones H4 and H2A. Specifically recognizes and binds acylated histone H3, with a preference for histone H3 diacetylated at 'Lys-18' and 'Lys-27' (H3K18ac and H3K27ac) or histone H3 diacetylated at 'Lys-14' and 'Lys-27' (H3K14ac and H3K27ac). Also able to recognize and bind crotonylated histone H3. May also recognize and bind histone H3 succinylated at 'Lys-122' (H3K122succ); additional evidences are however required to confirm this result in vivo. Plays a key role in histone variant H2AZ1/H2A.Z deposition into specific chromatin regions: recognizes and binds H3K14ac and H3K27ac on the promoters of actively transcribed genes and recruits NuA4-related complex to deposit H2AZ1/H2A.Z. H2AZ1/H2A.Z deposition is required for maintenance of embryonic stem cell (By similarity).
Synonyms: Gas41; NuBI-1; YAF9; 4930573H17Rik; B230215M10Rik
Tractability: Small molecule: a structure with a bound ligand is known. PROTAC: UniProt records ubiquitination sites on it; ubiquitination databases record sites on it; its protein half-life has been measured.
Target class: YEATS domain; Epigenetic regulator; Reader
Chemical probes: PFI-8 (high quality)
Gene: Protein-coding gene on chromosome 12 (69,359,710 to 69,390,870, forward strand). Ensembl gene ENSG00000127337.
Subcellular location: Nucleus
Subcellular location (Human Protein Atlas): Nucleoplasm; Nuclear membrane
Pathways (Reactome):
Chromatin organization: HATs acetylate histones
Gene expression (Transcription): Activation of the TFAP2 (AP-2) family of transcription factors
Gene Ontology:
Molecular function: histone H3K18ac reader activity; histone H3K27ac reader activity; protein binding; histone binding; structural constituent of cytoskeleton
Biological process: positive regulation of double-strand break repair via homologous recombination; regulation of cell cycle; chromatin remodeling; mitotic cell cycle; positive regulation of DNA-templated transcription; regulation of apoptotic process; regulation of DNA-templated transcription; regulation of double-strand break repair; regulation of transcription by RNA polymerase II; cytoskeleton organization
Cellular component: NuA4 histone acetyltransferase complex; nucleoplasm; nucleosome; nucleus; nuclear matrix
Genetic constraint (gnomAD): Loss-of-function variants: 16 observed, 27.68 expected, observed/expected ratio (o/e) 0.58, 90% interval 0.39 to 0.88. The upper end of that interval is the gene's LOEUF score, 0.88, which puts it in group 3 of 6, group 1 being the genes least tolerant of losing a copy. Missense variants: 140 observed, 266.82 expected, observed/expected ratio (o/e) 0.52, 90% interval 0.46 to 0.6. Synonymous variants: 84 observed, 88.57 expected, observed/expected ratio (o/e) 0.95, 90% interval 0.79 to 1.14.
Homologues: Orthologues: chimpanzee YEATS4 (100% identical), macaque YEATS4 (100% identical), guinea pig YEATS4 (99% identical), mouse Yeats4 (99% identical), dog YEATS4 (99% identical), pig YEATS4 (99% identical), rat Yeats4 (99% identical), tropical clawed frog yeats4 (96% identical), zebrafish yeats4 (91% identical).
Diseases named in the same sentence as YEATS4 in open-access papers:
YEATS4 is named in the same sentence as 31 diseases in open-access papers, as found by Europe PMC text mining. Sharing a sentence is not in itself a finding about the gene and the disease. The quoted sentences say what the papers report.
glioma (15 papers, 2004 to 2025). A benign or malignant brain and spinal cord tumor that arises from glial cells (astrocytes, oligodendrocytes, ependymal cells). "Though some report demonstrate silencing of YEATS4/GAS41 is capable of inducing apoptosis, but studies relating to association of miR-203 and GAS41 in glioma progression and apoptosis are still in its infancy." (PMID 27467502, 2016). "YEATS4, also known as GAS41, is a nuclear protein encoded by the GAS41 (glioma-amplified sequence) gene that was identified in a glioblastoma cell line." (PMID 34068344, 2021). "Another gene is YEATS4 (GAS41; glioma amplified sequence), which has high expression in the human brain and is frequently amplified in gliomas." (PMID 18664255, 2008).
colorectal cancer (8 papers, 2016 to 2025). A primary or metastatic malignant neoplasm that affects the colon or rectum. "The three-hit model has shown to be applicable in APC in colorectal cancer, and it can be speculated whether this same model could be applicable for YEATS4 and DMAP1 in case of mutations with possible residual activity." (PMID 36773604, 2023). "When YEATS4 is knocked down in colorectal cancer cells, the cells are arrested in the G0/G1 phase and cell growth is inhibited." (PMID 37435030, 2023). "For example, downregulation of YEATS4 promoted cell apoptosis in colorectal cancer cells." (PMID 29706630, 2018). "Subsequent studies have indicated that miR-218 can negatively regulate YEATS4 expression, thereby attenuating cellular resistance to L-OHP, impairing cellular autophagy protection, and inhibiting colorectal cancer progression." (PMID 37435030, 2023). "The YEATS Domain Containing 4 (YEATS4), instead, is found to be overexpressed in several human cancers, such as lung adenocarcinoma, glioblastoma, and colorectal cancer (CRC), promoting cell proliferation through the inhibition of senescence and an increase in multipolar mitotic spindle formation." (PMID 30634442, 2019).
glioblastoma (8 papers, 2016 to 2025). The most malignant astrocytic tumor (WHO grade IV). "In glioblastoma, YEATS4 can cooperate with n-Myc and c-Myc through its C-terminus and can also be repressed by miR-203, which in turn mediates a decrease in miR-10b expression." (PMID 37435030, 2023). "In summary, YEATS4 overexpression is involved in the development of many cancers, including glioblastoma." (PMID 37435030, 2023). "As a member of a relatively newly discovered epigenetic reading protein family, characterized by the presence of N-terminal YEATS domain, YEATS4 was first identified and isolated from glioblastoma in 1997; therefore, it is also known as the glioma amplification gene (GAS41)." (PMID 37435030, 2023).
non-small cell lung carcinoma (7 papers, 2015 to 2025). A group of at least three distinct histological types of lung cancer, including non-small cell squamous cell carcinoma, adenocarcinoma, and large cell carcinoma.
breast carcinoma (5 papers, 2022 to 2024). "YEATS4 overexpression enhances the malignant features of breast cancer cells, especially inducing epithelial-to-mesenchymal transition, and YEATS4 is associated with poor prognosis in breast cancer." (PMID 36171897, 2022). "It is reported that YEATS4 regulates the expression of ZEB1 in breast cancer, promotes EMT and metastasis, and is related to poor prognosis." (PMID 38164285, 2024). "In contrast, TACC2 binds to and inhibits YEATS4 in breast cancer cell lines, attenuating tumor growth and migration." (PMID 37435030, 2023). "In breast cancer, YEATS4 recognizes histone H3K27ac in the promoter region of ZEB1, thereby promoting ZEB1 expression and accelerating tumor progression." (PMID 37435030, 2023). "YEATS4 has been described as an oncogene in several cancer types, interacts directly with MYC and has been implicated in migration and invasion in breast cancer through regulation of miRNAs." (PMID 36860495, 2022). "Dysregulation of the human transforming acidic coiled-coil (TACC) protein is associated with the development and progression of breast cancer, where both TACC1 and TACC2 bind to YEATS4 to form complexes that affect the growth and proliferation of breast cancer cells." (PMID 37435030, 2023). "Additionally, TACC1 and YEATS4 regulate the expression of downstream target genes and accelerate breast cancer malignancy." (PMID 37435030, 2023). "In breast cancer, YEATS4 recognizes H3K27ac in the ZEB1 promoter and promotes EMT in breast cancer cells." (PMID 37435030, 2023).
lung carcinoma (4 papers, 2016 to 2024). "YEATS4 amplification samples show increased mRNA levels of several well-known antioxidant genes, including NQO1, SLC7A11, and GCLC, suggesting beside NFE2L2 mutation and KEAP1 mutation, YEATS4 amplification could be the other critical genetic marker in lung cancer by modulating antioxidant pathways." (PMID 38514704, 2024). "Another article showed the proof that overexpression of YEATS4 abrogated senescence in human bronchial epithelial cells, while RNAi-mediated attenuation of YEATS4 could conversely reduce lung cancer cells proliferation and tumor growth, impair colony formation, and induce cellular senescence." (PMID 27028764, 2016).
pancreatic cancer (4 papers, 2017 to 2025). "In this study, we have examined the expression pattern of YEATS4 in pancreatic cancer, investigated the functions of YEATS4 and elucidated the underlying molecular mechanism." (PMID 28445953, 2017). "Taken together, these observations indicated that YEATS4 promoted the metastasis of pancreatic cancer cells and was necessary for the malignant transformation of normal pancreatic cells." (PMID 28445953, 2017). "In summary, these data suggested that YEATS4 promoted the migration, colony formation and invasion of pancreatic cancer cells by activating beta-catenin/TCF signaling." (PMID 28445953, 2017). "In this study, we have demonstrated that YEATS4 promoted the growth, migration and invasion of pancreatic cancer cells by activating beta-catenin/TCF signaling." (PMID 28445953, 2017). "In the present study, YEATS4 was up-regulated in the pancreatic cancer mouse model, knocking down the expression of YEATS4 impaired the malignant transformation of normal pancreatic cells HPDE6C7, and YEATS4 is a target and effector of oncogenic Ras signaling." (PMID 28445953, 2017). "In summary, our study demonstrated that YEATS4 promoted the progression of pancreatic cancer by activating beta-catenin/TCF signaling." (PMID 28445953, 2017). "Collectively, these results demonstrated that YEATS4 promoted the growth, migration, colony formation and invasion of pancreatic cancer cells." (PMID 28445953, 2017). "To explore the underlying mechanisms for the oncogenic roles of YEATS4 in the pancreatic cancer, we screened the effects of YEATS4 on the activity of several pathways using lusiferase reporter assay." (PMID 28445953, 2017). "The expression of YEATS4 was elevated in clinical pancreatic cancer samples and pancreatic cancer mouse model." (PMID 28445953, 2017). "Up-regulation of YEATS4 promoted the growth, migration and invasion of pancreatic cancer cells, while knocking down the expression of YEATS4 inhibited the growth, migration, invasion and metastasis of pancreatic cancer cells." (PMID 28445953, 2017). "Considering the nuclear localization of YEATS4 in the pancreatic cancer, we first tested the interaction between YEATS4 and beta-catenin/TCF4 transcriptional machinery." (PMID 28445953, 2017). "To study the expression profile of YEATS4 in the pancreatic cancer, we first turned to the Oncomine Database." (PMID 28445953, 2017). "Next, we examined the protein level of YEATS4 in human pancreatic cancer samples by immunohistochemistry staining and western blot analysis." (PMID 28445953, 2017). "To better understanding the roles of YEATS4 in pancreatic cancer, we knocked down its expression in HPAC and Capan-1 cells using two independent si RNA sequence." (PMID 28445953, 2017). "The effects of YEATS4 on the growth, migration, colony formation and invasion of pancreatic cancer cells were evaluated by MTT assay, Boyden chamber and soft agar assay, respectively." (PMID 28445953, 2017). "Comparing with the normal pancreatic cells (HPDE6C7), up-regulation of YEATS4 in pancreatic cancer cells (HPAC, SW1990, MiaPaca2, PANC-1 and Capan-1) was observed." (PMID 28445953, 2017). "It was found that upregulation of YEATS4 in pancreatic cancer promotes the growth, proliferation, and migration of pancreatic cancer cells, and impairs the action of oncogenic Ras after knockdown of the YEATS4 gene, which inhibits the proliferation and transformation of pancreatic cancer cells." (PMID 37435030, 2023). "Additionally, we examined the YEATS4 protein level in normal pancreatic cells and a panel of pancreatic cancer cell lines." (PMID 28445953, 2017). "Taken ogether, these data suggested the up-regulation of YEATS4 in the pancreatic cancer." (PMID 28445953, 2017). "Furthermore, elevated YEATS4 protein level was observed in about 70% (5/7) pancreatic cancer samples in the western blot analysis." (PMID 28445953, 2017).
pancreatic cancer (continued). "In this study, knocking down YEATS4 has shown to down-regulate the expression of Snail, a master of EMT (epithelial-mesenchymal transition), suggesting that YEATS4 might promote the motility of pancreatic cancer cells by inducing EMT." (PMID 28445953, 2017). "The expression of YEATS4 was increased in the clinical pancreatic cancer samples, which was confirmed by the oncomine database and our experimental results, suggesting that YEATS4 might be diagnosis marker for PDAC." (PMID 28445953, 2017). "Two independent studies have shown the up-regulation of YEATS4 in the pancreatic cancer." (PMID 28445953, 2017). "Taken together, our study demonstrated the oncogenic roles of YEATS4 in the progression of pancreatic cancer by activating beta-catenin/TCF signaling and suggested that YEATS4 might be a promising therapeutic target for pancreatic cancer." (PMID 28445953, 2017). "The accumulation of YEATS4 in the cytoplasm and nucleus of pancreatic cancer cells was found." (PMID 28445953, 2017). "Moreover, we examined the protein level of YEATS4 in the pancreatic cancer mouse model (Pdx-Cre; L-S-L-RasG12D), which was driven by the oncogenic RasG12D." (PMID 28445953, 2017). "Moreover, the up-regulation of YEATS4 in the pancreatic cancer mouse model prompted us to investigate whether YEATS4 was essential for the transformation of HPDE6C7 driven by RasG12D." (PMID 28445953, 2017). "To examine whether YEATS4 promoted the migration, invasion and anchorage-independent growth of pancreatic cancer cells through activating beta-catenin/TCF signaling, we investigated whether dominant negative beta-catenin (DN beta-catenin) could rescued the biological functions of YEATS4." (PMID 28445953, 2017). "Therefore, YEATS4 might be a promising therapeutic target for pancreatic cancer." (PMID 28445953, 2017). "To study the roles of YEATS4 in the tumorigenesis of pancreatic cancer, we first over-expressed YEATS4 in HPAC and Capan-1 cells and confirmed the exogeneous expression of YEATS4 (myc-YEATS4) by western blot analysis." (PMID 28445953, 2017). "Knocking down the expression of YEATS4 in HPAC and Capan-1 cells inhibited the growth of cancer cells in liquid culture, as well as the migration and invasion of pancreatic cancer cells based on the Boyden chamber assay." (PMID 28445953, 2017). "YEATS4 can bind to H2A.Z2, which in turn drives the activation of NOTCH1, upregulates the expression of NOTCH1 and its downstream mediator Hes1, and mediates the occurrence and drug resistance of pancreatic cancer." (PMID 37435030, 2023). "We further confirmed the up-regulation of YEATS4 by examining the mRNA level of YEATS4 in 31 pancreatic cancer clinical samples and 31 adjacent non-cancerous tissues." (PMID 28445953, 2017).
gastric cancer (3 papers, 2023 to 2024). A primary or metastatic malignant neoplasm involving the stomach. "YEATS4 is also associated with tumor size, depth, distant metastasis, and poor prognosis, suggesting that YEATS4 could be a target for developing oncological drugs and improving the prognosis of gastric cancer." (PMID 37435030, 2023). "In gastric cancer, upregulated YEATS4 directly acts on β-catenin to activate its transcription, thereby promoting the protein expression of β-catenin and inducing its phosphorylation." (PMID 37435030, 2023). "In addition, overexpression of YEATS4 in gastric cancer cells activates NOTCH2, promoting cancer cell proliferation and poor prognosis." (PMID 37435030, 2023).
hepatocellular carcinoma (3 papers, 2018 to 2023). A malignant tumor that arises from hepatocytes. "Mechanistically, lncAKHE cooperated with YEATS4 to enhance the activation of NOTCH2 signaling which is usually abnormally upregulated in hepatocellular carcinoma." (PMID 29706630, 2018).
liposarcoma (3 papers, 2021 to 2023). A usually painless malignant tumor that arises from adipose tissue. "YEATS4 and CPM are known to be associated with the dedifferentiation of liposarcoma." (PMID 33498189, 2021). "In liposarcomas, MDM2 and YEATS4 amplifications appear to be particularly important and can form characteristic giant ring or giant rod marker chromosomes, suggesting that YEATS4 can be used as a diagnostic and therapeutic target for liposarcoma (Mashima, Sawada, Nakamura)." (PMID 37435030, 2023).
ovarian carcinoma (3 papers, 2015 to 2023). A malignant neoplasm originating from the surface ovarian epithelium. "Further, of the 93 ovarian cancer genes regulated by TFEB1 and YEATS4, 11 (12%) were commonly associated by both these TFs." (PMID 26307679, 2015). "YEATS4 and TFEB1 have been shown to be upstream transcription factors (TFs) that regulate drug resistance in ovarian cancer, which is an important factor contributing to poor treatment outcomes in ovarian cancer." (PMID 37435030, 2023). "Further, combination treatment of ovarian cancer cells with TFEB1 and YEATS4 siRNAs resulted in 35% reversal of drug resistance." (PMID 26307679, 2015). "Two TFs YEATS4 and TFEB1 were anticipated to be the common upstream regulators that conferred drug resistance to ovarian cancer cells." (PMID 26307679, 2015). "YEATS4 and TFEB1 have been shown to be upstream transcription factors in ovarian cancer." (PMID 37435030, 2023). "Next, we determined whether YEATS4 decreased drug resistance of ovarian cancer cells by treating HeyA8-MDR and A2780-CP cells with YEATS4 siRNA." (PMID 26307679, 2015). "Thus, we suggest a novel approach to reverse chemoresistance of ovarian cancer by suppressing TFEB1 and YEATS4." (PMID 26307679, 2015). "Although we may have missed other TFs, TFEB1 and YEATS4 are not likely to be mispredicted as being involved in conferring drug resistance to ovarian cancer cells." (PMID 26307679, 2015).